ZC3H12B (zinc finger CCCH-type containing 12B)
Description:
May function as RNase and regulate the levels of target RNA species.
Synonyms: CXorf32; MCPIP2
Tractability: PROTAC: ubiquitination databases record sites on it.
Gene: Protein-coding gene on chromosome X (65,034,788 to 65,507,887, forward strand). Ensembl gene ENSG00000102053.
Subcellular location (Human Protein Atlas): Nucleoli fibrillar center; Golgi apparatus
Gene Ontology:
Molecular function: mRNA binding; RNA endonuclease activity; metal ion binding
Biological process: 3'-UTR-mediated mRNA destabilization
Cellular component: cytoplasmic ribonucleoprotein granule; nucleus
Homologues: Orthologues: chimpanzee ZC3H12B (99% identical), macaque ZC3H12B (99% identical), rabbit ZC3H12B (96% identical), pig ZC3H12B (93% identical), mouse Zc3h12b (91% identical), rat Zc3h12b (91% identical), tropical clawed frog zc3h12b (74% identical), zebrafish zc3h12b (65% identical), dog ZC3H12B (57% identical), Caenorhabditis elegans rege-1 (24% identical), Drosophila melanogaster Regnase-1 (22% identical), Drosophila melanogaster CG42360 (12% identical), and 3 more. Paralogues in human: ZC3H12C (53% identical), ZC3H12A (32% identical), ZC3H12D (25% identical), NYNRIN (17% identical), N4BP1 (15% identical), KHNYN (14% identical).
Diseases named in the same sentence as ZC3H12B in open-access papers:
ZC3H12B is named in the same sentence as 10 diseases in open-access papers, as found by Europe PMC text mining. Sharing a sentence is not in itself a finding about the gene and the disease. The quoted sentences say what the papers report.
colon cancer (6 papers, 2021 to 2025). "The downregulation or loss of ZC3H12B in colon cancer cells results in a more aggressive tumor, increased growth, invasion, and worse prognosis." (PMID 41357196, 2025). "As a result, the current study set out to explore whether M2 macrophage-derived exosomal miR-155-5p regulates immune escape in colon cancer and the underlying mechanisms involving ZC3H12B." (PMID 33718596, 2021). "One of the proteins is ZC3H12B, which is a tumor suppressor in colon cancer, regulating inflammation and cell proliferation." (PMID 41357196, 2025). "Mechanistically, when miR-155-5p is delivered from M2 macrophages to colon cancer cells via exosomes, it disrupts the ability of ZC3H12B to reduce the stability of IL-6, resulting in immune evasion and tumor formation." (PMID 37981718, 2023). "In colon cancer cells, the overexpression of miR-155-5p and IL-6, along with the reduced expression of zinc-finger-type-containing 12B (ZC3H12B), promotes the progression of colon cancer." (PMID 37981718, 2023). "It has also been shown that miR-155-5p in M2 macrophages derived exosomes after transfer to colon cancer cells by targeting zinc-finger-type-containing 12B (ZC3H12B) leads to increased IL-6 expression, immune escape and tumor progression in colon cancer." (PMID 35550636, 2022). "These experimental data confirmed that miR-155-5p functioned through IL-6 and then regulated ZC3H12B, thus affecting immune escape of colon cancer." (PMID 33718596, 2021). "Altogether, findings obtained in our study concluded that M2 macrophage-derived exosomes transferred miR-155-5p into colon cancer cells to target ZC3H12B, which increased IL-6 expression and then promoted immune escape and tumor formation in colon cancer." (PMID 33718596, 2021). "miR-155-5p was transferred by M2 macrophage-derived exosomes into colon cancer cells, where miR-155-5p targeted ZC3H12B, which in turn negatively regulated the stability of IL-6 mRNA." (PMID 33718596, 2021). "Delivery of miR-155-5p from M2 macrophage to colon cancer cells through exosomes impaires ZC3H12B-mediated IL-6 stability reduction, which consequently induced immune escape and tumor formation." (PMID 34722637, 2021). "M2 macrophage-derived exosomal miR-155-5p promotes the development of colon cancer by inhibiting the expression of ZC3H12B in vivo." (PMID 34722637, 2021). "Together, these results indicated that miR-155-5p carried by M2 macrophage-derived exosomes could promote the immune escape of colon cancer cells through the regulation of ZC3H12B." (PMID 33718596, 2021). "It was found that ZC3H12B was poorly expressed in colon cancer tumor tissues and cells." (PMID 33718596, 2021). "In order to further investigate the effect of M2 macrophage-derived exosomal miR-155-5p on immune escape in colon cancer, we treated the exosomes derived from M2 macrophages with miR-155-5p inhibitor, and ZC3H12B was overexpressed in SW48 cells treated with exo-miR-155-5p inhibitor." (PMID 33718596, 2021). "Based on this data, we speculated whether ZC3H12B affected the development of colon cancer by regulating IL-6." (PMID 33718596, 2021). "Collectively, our findings indicated that M2 macrophage-derived exosomal miR-155-5p can potentially promote the immune escape of colon cancer by impairing ZC3H12B-mediated IL-6 stability reduction, thereby promoting the occurrence and development of colon cancer." (PMID 33718596, 2021). "Our initial results indicated that ZC3H12B affected immune escape through IL-6, but whether miR-155-5p promotes immune escape through the regulation of ZC3H12B in colon cancer remained unclear." (PMID 33718596, 2021). "Moreover, another critical finding in the current study was that the transfer of miR-155-5p into colon cancer cells via M2 macrophage-derived exosomes to target ZC3H12B diminished the expression levels of IL-6." (PMID 33718596, 2021).
colon cancer (continued). "Additionally, miR-155-5p could be transferred by M2 macrophage-isolated exosomes to colon cancer cells, which targeted ZC3H12B by binding to the 3¢ UTR, as identified by dual luciferase reporter gene." (PMID 33718596, 2021). "Moreover, after miR-155-5p is transferred to colon cancer cells through M2 MDEs, it targets ZC3H12B and negatively regulates the stability of IL-6 mRNA, increases IL-6 release by tumor cells, and suppresses T-cell immune responses, promoting immune escape in colon cancer." (PMID 40612677, 2025). "Subsequently, qRT-PCR was performed to determine the mRNA expression patterns of ZC3H12B in colon cancer tumor and adjacent normal tissues and SW48 colon cancer cells and CCD841CoN human normal colon epithelial cells." (PMID 33718596, 2021). "Consequently, we speculated that miR-155-5p may play a role in colon cancer via ZC3H12B regulation." (PMID 33718596, 2021).
glioma (2 papers, 2021 to 2024). A benign or malignant brain and spinal cord tumor that arises from glial cells (astrocytes, oligodendrocytes, ependymal cells). "Regnase-2 (Reg-2/MCPIP2/ZC3H12B) is uniquely expressed at a high level in the healthy brain and down-regulated in samples from patients with glioma, reaching the lowest level in high-grade glioblastoma multiforme (GBM)." (PMID 38238463, 2024).
co-infection (1 paper, 2021). "On the contrary, co-infection of miR-320a with the ZC3H12B 3ʹUTR mutant exhibited no significant change, suggesting that the binding of miR-320a to ZC3H12B is straightforward." (PMID 35201481, 2021).
meningioma (1 paper, 2020). A generally slow growing tumor attached to the dura mater. "Six potentially pathogenic mutations in PHRF1, ZC3H12B, H2AFV, DNAJC13, DNAH8, SCN2A were non-recurrent; however, given the modest sample size it is difficult to fully evaluate the importance of these variants in the meningioma progression." (PMID 32724039, 2020).
neuroblastoma (1 paper, 2021). Neuroblastoma (NB) is the most common solid, extracranial childhood tumor. "The mRNA level of ZC3H12B was found to be increased in the neuroblastoma cell line SH-SY5Y and human brain." (PMID 35201481, 2021).
ovarian carcinoma (1 paper, 2021). A malignant neoplasm originating from the surface ovarian epithelium. "On the contrary, the down regulated EV-derived miR-320a suppressed tumorigenesis, invasion, and angiogenesis of ovarian cancer by directly targeting a novel target, ZC3H12B." (PMID 35201481, 2021). "In conclusion, it is the first time to propose the idea that EV-derived miR-320a directly binds to ZC3H12B to exert its antitumor effect in ovarian cancer." (PMID 35201481, 2021). "An unreported role of ZC3H12B in promoting ovarian cancer cell proliferation has been elucidated and miR-320a could mediate the expression of ZC3H12B, thereby inhibiting the downstream response." (PMID 35201481, 2021). "Lower expression of EV-derived miR-320a and higher expression of ZC3H12B correlate with shorter survival period, indicating that EV-derived miR-320a may also serve as a prognostic biomarker in ovarian cancer." (PMID 35201481, 2021).
tumor (5 papers, 2021 to 2025). "Taken together, these findings indicated that miR-155-5p transferred by M2 macrophage-derived exosomes promoted the expression of IL-6 expression through downregulation of ZC3H12B, thus inhibiting T cell immune response and promoting tumor formation." (PMID 33718596, 2021). "Xenograft models confirmed that M2 macrophage-derived exosomal miR-155-5p reduced the ZC3H12B expression to upregulate IL-6, which consequently induced immune escape and tumor formation." (PMID 33718596, 2021). "In one study, the elevated level of ZC3H12B distorts tumor progression by trapping the cell cycle in the G2 phase." (PMID 35201481, 2021). "We further detected the expression patterns of miR-155-5p, ZC3H12B, and IL-6 in tumor tissues of mice." (PMID 33718596, 2021). "At the same time, the expression patterns of ZC3H12B, T cell markers CD4 and CD8, M1 type markers CD14 and CD86, and M2 type markers CD163 and CD206 were also detected in mouse tumor tissues." (PMID 33718596, 2021).
ZC3H12B also shares sentences with these, for which no sentence is quoted: cancer (2 papers); chronic hepatitis B (1); glioblastoma multiforme (1).